ATG5 (autophagy related 5)
Diseases named in the same sentence as ATG5 in open-access papers (continued):
Sharing a sentence is not in itself a finding about the gene and the disease.
cancer (continued). "Finally, we provide evidence that ATG16L2, which is overexpressed in several cancers relative to ATG16L1, hijacks the conjugation switch by competing with ATG16L1 for binding to ATG5." (PMID 31636955, 2019). "Increased expression of the autophagy-related proteins Atg5, Atg7, Atg12, p62, and LC3 enhanced autophagy, which would degrade inadequate protein aggregates and also provide nutrients for rapidly growing cancer cells." (PMID 28358375, 2017). "Atg5 and LC3II/I were the indicators for the autophagy of cancer cells." (PMID 29088814, 2017). "Recent studies have suggested a correlation among autophagic markers such as LC3B, p62, Atg5, and active STAT3 in some human cancers, among which the cancers with the higher STAT3 expression showed increased expression of autophagic markers and exhibited the worst outcome." (PMID 27474168, 2016). "Recent studies have suggested a correlation among autophagic markers such as LC3B, p62, Atg5, and active STAT3 in some human cancers, among which the cancers with the highest STAT3 expression showed an increased expression of autophagic markers and had the worst outcome." (PMID 27474168, 2016). "Considering the closest flanking genes of intergenic SNPs, the following are noteworthy and could contribute to the carcinogenic process, as has been reported for other cancer types: PRDM1, ATG5, MYC, EID, RLN1, CD274." (PMID 23626673, 2013). "While PIKfyve inhibition elevated MHC-I surface expression in wild-type cells, it did not further increase surface expression of MHC-I in the Atg5-null or Atg7-null cancer cells, confirming that PIKfyve inhibition upregulated MHC-I surface expression by impairing autophagy." (PMID 38011559, 2023). "Indeed, recent studies in skeletal muscle and cancer cells reported that pharmacological activation of REV-ERBα inhibits autophagosome formation via negative modulation of core autophagy genes such as Ulk3, Ulk1, Bec1, Atg7, and Atg5." (PMID 35428762, 2022). "Thus, MAA may have enhanced the anti-cancer activity of CTX and Atg5 siRNA may have mediated the downregulation of autophagy due to ROS generation and activation of the mitochondrial apoptosis pathway." (PMID 27043621, 2016). "However, since ATG5 has several highly cancer-relevant non-autophagic functions, it will be essential to evaluate whether the increase in migration, invasion and metastasis that was observed upon ATG5 knockdown also occurs upon knockdown of other central ATGs." (PMID 38910881, 2024). "In addition, the expression levels of autophagy markers such as Beclin-1, ATG5, ATG7, and LC3II conversion were significantly higher in human tumors compared to adjacent nontumor tissues, demonstrating the correlation with upregulation of autophagy function in cancer cells." (PMID 33806593, 2021). "However, the association between ATG5 and CDKL3 in cancer has not been studied previously." (PMID 32974198, 2020). "Moreover, mouse cancer cells stably expressing a constitutively active AKT enzyme (or lacking the essential autophagy gene Atg5) became resistant against the anticancer activity of ISO combined with ICD induction, suggesting some sort of ‘specificity’ for the ISO effect." (PMID 33243998, 2020). "Although previous studies have shown that EVA1A regulates autophagy through ATG5 and mTOR/RPS6KB1 pathways in cancer, the mechanism of EVA1A regulating autophagy in cancer is not completely clear and needs to be further clarified." (PMID 35743108, 2022). "Similarly, mouse strains lacking the essential autophagic genes ATG5 and ATG7 develop liver damage, inflammation and benign liver tumors unable to progress to carcinoma." (PMID 30067838, 2018).
infection (157 papers, 2009 to 2025). The state of being infected such as from the introduction of a foreign agent such as serum, vaccine, antigenic substance or organism. "These and other activities of ATG5 underly the unique and often perplexing phenotypic manifestations of ATG5 observed in cells and in murine infection models, which served as the initial impetus for the present study." (PMID 39773872, 2025). "The intrinsic effect of autophagy on cell survival during infection was also shown in MEFs deficient for the major autophagy gene ATG5." (PMID 40042894, 2025). "Upon PAO1 infection, deficiency of Atg5 in AEC2 reduced the survival rate, resulting in a mortality rate of 45% for Atg5ΔAEC2 mice, while WT mice exhibited a mortality rate of 13% after 72 h." (PMID 40529614, 2025). "These and other activities of ATG5 underly the unique and often perplexing phenotypic manifestations of ATG5 observed in cells and in murine infection models 35,46,51,53–56, which served as the initial impetus for the present study." (PMID 39026874, 2024). "While atg5 mutant displayed similar susceptibility to the WT, the atg2 mutant exhibited accelerated leaf senescence and enhanced susceptibility upon infection." (PMID 33574453, 2021). "Some of ATGs knockout mutations exhibited enhanced susceptibility to pathogen infection, such as atg2, atg5, atg6, atg7, atg9, atg10, and atg18." (PMID 34829975, 2021). "Herein, we demonstrate that mice deficient in the Atg5-myeloid lineage show increased survival and less severe organ pathology upon infection with F. tularensis LVS." (PMID 33036147, 2020). "After infection of Atg5-deficient mice with 5 × 104 CFU/mouse, mice started to die at day 7 after infection." (PMID 33036147, 2020). "The location of the bacteria within the cells in the tissues of the spleen, liver, and lungs in the control mice and the Atg5-deficient mice was determined by transmission electron microscopy at 20 and 48 h after the infection." (PMID 33036147, 2020). "Collectively, our results show that the intradermal infection of Atg5-deficient mice with the LVS at the doses of 5 × 105 CFU/mouse, 5 × 106 CFU/mouse and 5 × 107 CFU/mouse resulted in 70%, 50% and 30% survival, respectively." (PMID 33036147, 2020). "The mean time to death of Atg5-deficient mice after infection with 5 × 108 CFU per mouse was 4 days and of control mice 3.5 days." (PMID 33036147, 2020). "In the liver tissue, 20 h after infection of Atg5-deficient mice and control group of mice, 82% and 9% of the bacteria were in the cytosol of the hepatocytes, respectively (p = 0.0001)." (PMID 33036147, 2020). "Our study showed that intradermal infection of Atg5-deficient mice with the LVS resulted in a higher survival rate than in the wild-type mice." (PMID 33036147, 2020). "In mice, knockout of autophagy protein Atg5 in macrophages and neutrophils increases susceptibility to infection with L. monocytogenes and the protozoan T. gondii." (PMID 28748360, 2017). "Results showed that the infection rate was dropped significantly in the autophagy-deficient Atg5−/− MEF compared to the wild-type MEF." (PMID 27558165, 2016). "Deficient ATG5 mice exhibit more severe inflammation and succumb earlier to the infection." (PMID 39949719, 2024). "Furthermore, bacterial burdens in organs of Atg5-deficient mice were significantly lower and the infection caused less severe histopathological changes within the organs in comparison to wild-type mice." (PMID 33036147, 2020). "Furthermore, the number of bacteria in the spleen of the control mice reached 2 × 106 CFU/mL by 72 h after infection, while the number of bacteria in the spleen of the Atg5-deficient mice was 2 × 105 CFU/mL (p = 0.013) (n = 3)." (PMID 33036147, 2020). "The infection of Atg5-deficient mice with Francisella tularensis subsp." (PMID 33036147, 2020).
infection (continued). "In the lung tissues of the Atg5-deficient mice, the infiltration of mononuclear cells and the parenchyma destruction were present to a greater extent at 72 h than at 48 h after infection; however, with less intensity in comparison to the control mice (p = 0.027)." (PMID 33036147, 2020). "Many years ago, the crucial in vivo role of autophagy in defense against pathogens has been demonstrated in mice knockout of autophagic factor Atg5 in monocytes/macrophages, which have been found to be susceptible to infection with Listeria monocytogenes and Toxoplasma gondii." (PMID 30234114, 2018). "Alternatively, this increase in log CFU could be linked to a lower bactericidal capacity of Atg5-deficient cells compared to WT cells at early stages of infection." (PMID 25179110, 2014). "However, autophagy-deficient MEFs (Atg5−/−) and WT cells with an impairment in lysosomal acidification surrendered to infection." (PMID 19242543, 2009). "Autophagy-deficient Atg5−/− MEFs and lysosomal acidification impaired cells surrender to infection." (PMID 19242543, 2009). "Other studies using a murine model have shown that knockout of Atg5 in macrophages and neutrophils increases susceptibility to L. monocytogenes infection and neuron-specific Atg5 knockout increases susceptibility to infection by central nervous system Sindbis virus." (PMID 32121251, 2020). "To test definitively whether autophagy was necessary for the targeting of ubiquitin-associated WT Mm to LAMP-1 positive vacuoles, we assessed infection of Atg5−/− mouse embryo fibroblasts, since Atg5 is a required component of the pathway for autophagosome formation." (PMID 19436699, 2009). "Next, the infected control and atg5 knockdown larvae were homogenized and the number of bacteria within individual larvae were enumerated over the course of the infection." (PMID 40987772, 2025). "Immunofluorescence further illustrated augmented expression of NT‐GSDMD in cells transfected with Atg5 siRNA compared to those transfected with control siRNA upon infection." (PMID 40529614, 2025). "IFITM3 overexpression up-regulated LC3B II/LC3B I, Beclin-1, ATG7, and ATG5, but down-regulated p62 during infection." (PMID 40681213, 2025). "Canonical autophagy, mediated by ATG proteins such as ATG5, restricts Mtb survival in alveolar macrophages by promoting phagosome-lysosome fusion and suppressing neutrophil-driven inflammation during early infection." (PMID 40487315, 2025). "The impairment of infection was particularly notable in the U-87 MG cell line, where the percentage of infected cells was five times lower in ATG5 KO cells." (PMID 38915300, 2024). "To evaluate the impact of ATG5 deletion on HSV-1 infection, we monitored the progression of the infection in WT and ATG5 KO cells by viral production titration and flow cytometry." (PMID 38915300, 2024). "As HSV-1 infection was significantly impaired at 12 hpi, we sought to investigate the potential impact of ATG5 deletion on the initial stages of infection, starting by analyzing the transcription and/or replication of the viral genome." (PMID 38915300, 2024). "In fact, in vivo models of infection highlight the role of xenophagy in intracellular pathogen clearance, as knocking down essential autophagy genes, like Atg5 or Atg16L1, increases bacterial load in mice infected with Salmonella59,60." (PMID 40395298, 2023). "Infection of ATG16L KD or ATG5 KD cells with the reporter virus resulted in fewer cells expressing mNG compared with parental cells." (PMID 36622177, 2023). "In Arabidopsis, infection with B. cinerea induced the relative expression of ATG genes, and the atg5/7/18a mutations impaired resistance to B. cinerea by regulating the expression of genes related to SA/JA signaling." (PMID 37509842, 2023).
infection (continued). "We showed that PB disassembly induced by infection with KSHV required Atg5 and NDP52, suggesting an important role for KapB-mediated elevated autophagic flux and PB catabolism in regulating KSHV-associated inflammation." (PMID 36634147, 2023). "There is evidence that C. trachomatis induces autophagy in an ATG5-dependent manner at mid to late stages of development and through p62 at later times during infection." (PMID 37645379, 2023). "Beclin 1 and ATG5 proteins were significantly enhanced in ncp BVDV2‐infected cells compared to mock infection, whereas their expressions were decreased in 3‐MA‐treated ncp BVDV2‐infected cells." (PMID 36533845, 2023). "Conversely, excision of other core autophagy genes including Atg5, Atg7, Atg14, and Atg16l1 from the mice macrophages showed moderate to severe level vulnerability to pathogen infection and bacterial burden." (PMID 37180758, 2023). "Although similar numbers of B. cenocepacia CFUs were recovered at 4 h post-infection in atg5−/− mice lungs, which reflect an equal initial inoculum, these mice exhibited higher B. cenocepacia loads in their lungs at 48 h post-infection." (PMID 35252032, 2022). "The result suggested that the host Atg3 and Atg5 are binding proteins of CDPK3 during infection with the less virulent ME49 strain." (PMID 35757711, 2022). "ATG7, or ATG7 combined with ATG5 for an optimal effect, were thus targeted for silencing for 48 h prior to infection at two MOI (0.1 and 0.001)." (PMID 36298785, 2022). "In Rift Valley Fever Virus (RVFV) infection, silencing of autophagy proteins (Atg5, Atg7 and Becn1) has been shown to negatively affect the host antiviral response and increase viral replication." (PMID 36248895, 2022). "Contribution of some autophagy-related proteins (ATG16L1, ATG5, and ATG12) in lysosomal exocytosis was recently highlighted in the context of host cell infection by the Gram-positive pathogenic bacterium Listeria monocytogenes." (PMID 35086419, 2022). "Diverse picornaviruses, including foot-and-mouth disease virus (FMDV), invade by specifically recognizing and binding with cell surface receptors and rely on the ATG5 pathway to induce autophagy at the early stage of infection." (PMID 35978392, 2022). "During infection, increased expression of Atg5 and Atg12, potential inhibitors of RLR receptors, was demonstrated." (PMID 36248895, 2022). "Zika virus (ZIKV) triggers NF-κB-dependent inflammatory signaling in the fly brain and induces the expression of Atg5 and Atg7, leading to autophagy activation in neurons and limiting the infection and proliferation of ZIKV in this organ." (PMID 35159248, 2022). "PVs containing different numbers of tachyzoites in wild-type and atg5−/− HeLa cells at 18, 24, and 30 h post-infection were determined." (PMID 36532461, 2022). "In the fly brain, NF-κB induces the expression of Atg5 and Atg7, and thus triggers autophagy activation against infection with Zika virus." (PMID 35159248, 2022). "We intratracheally infected atg5−/− mice with B. cenocepacia K-56 strain and then harvested the lung, liver, and spleen at different time points post-infection." (PMID 35252032, 2022). "Our RT-qPCR results showed that infection with H. pylori decreased the expression of the autophagy genes (Beclin1, ATG5, and ATG12 expression decreased by 0.71-, 0.73-, and 0.68-fold, respectively) compared to the negative control group (1-fold)." (PMID 36139826, 2022). "Atg5 is an essential component of the autophagosome machinery, and increased Atg5 suggests autophagy activation during ΔPE_PGRS20 and ΔPE_PGRS47 infection." (PMID 34346699, 2021). "In infection with invasive E. coli, autophagy in neutrophils precedes neutrophil extracellular trap formation, and autophagy-related 5 silencing completely blocks neutrophil extracellular trap formation." (PMID 34638724, 2021).
infection (continued). "In infection with invasive bacteria, autophagy in neutrophils precedes neutrophil extracellular trap formation, and autophagy-related 5 knockdown blocks neutrophil extracellular trap formation." (PMID 34638724, 2021). "Messenger RNA levels of the autophagy-related genes were significantly elevated at most of the timepoints after infection, except for some genes (Bcl-2, Atg5, Atg12, DRAM1, and VMP1) whose transcription levels declined at 7 dpi." (PMID 33600403, 2021). "For instance, Beclin1, PI3K/VPS30, and ATG3 are all required to limit HR PCD to the pathogen infection site, ATG5 and ATG7 regulate glucose-induced ROS in Arabidopsis, and ATG9 is a negative regulator of innate immune signaling." (PMID 32373106, 2020). "At 6 h post infection (p.i.), the bacterial count in the spleen of the control group (1 × 103 CFU/mL) was slightly higher than in the spleen of the Atg5-deficient mice (3 × 102 CFU/mL) (p = 0.047) (n = 3)." (PMID 33036147, 2020). "A previous study on mouse embryonic fibroblasts has shown that autophagy provides nutrients to support the replication of F. tularensis during infection by an Atg5-independent autophagy pathway." (PMID 33036147, 2020). "S100A9, which is known to be upregulated during infection and inflammation, was also present in the ATG5 interactome." (PMID 33024031, 2020). "At 20 h post infection, 11% of the LVS bacteria were found in the cytosol of the control mice splenocytes which was significantly different from the Atg5-deficient mice where 71% of bacteria were in the cytosol of the splenocytes (p = 0.0001)." (PMID 33036147, 2020). "The only difference in survival rate was observed at the third day of infection, whereas 100% of Atg5 mice were alive in contrast to 70% of survival in control group of mice (p = 0.0006)." (PMID 33036147, 2020). "At 72 h after infection, the number of the LVS in the lung of the control mice declined to 2 × 104 CFU/mL, as well as the bacterial count in the lung of Atg5-deficient mice declined to 2 × 103 CFU/mL (p = 0.005) (n = 3)." (PMID 33036147, 2020). "CA16 infection significantly reduced the number of poly I:C-induced SGs, and knockdown of Atg5 rescued the degradation of the poly I:C-induced SGs, which was caused by CA16 infection." (PMID 32082291, 2020). "Although we observed increased expression levels of LC3-II and LC3 puncta in Atg5-competent BMMs, it remained unclear if autophagosomes were accumulated by infection with R. australis." (PMID 30297526, 2019). "Autophagy-related genes, including Atg5, have been reported to suppress proinflammatory cytokines in a variety of infection models (37, –, 40)." (PMID 30297526, 2019). "Intracellular infection of R. australis in primary mouse macrophages in vitro is also Atg5 dependent." (PMID 30297526, 2019). "Our results, more strikingly, recapitulated the in vitro Atg5-dependent infection by R. australis in macrophages in a mouse model of Rocky Mountain spotted fever." (PMID 30297526, 2019). "To further test the effect of autophagy in the LRV-mediated inhibition of inflammasome activation, we silenced ATG5 in primary BMDMs and assessed inflammasome activation in response to L.g.+ and L.g.− infection." (PMID 31754185, 2019). "This upregulation resulted in a 7-fold increase in ATG5 transcripts in the infected mice at 7 days post-infection." (PMID 29896527, 2018). "Following 5 h of infection, there is consistently more surviving bacteria in ATG5−/− cells than in wild type as previously reported." (PMID 29743550, 2018). "This escalation on quantification revealed a 4-fold increase in the levels of Atg5 in the C. albicans infected mice as compared to the uninfected mice at 7 days post-infection." (PMID 29896527, 2018). "Blocking protein synthesis with cycloheximide at 18 hours post-infection revealed slower ASC oligomer turnover in HtrA2- or ATG5-depleted cells than in control cells." (PMID 29855523, 2018).